CLDN1 (claudin 1)
Diseases named in the same sentence as CLDN1 in open-access papers (continued):
Sharing a sentence is not in itself a finding about the gene and the disease.
breast carcinoma (continued). "Our study has provided experimental evidence that lentiviral vector mediated RNA interference can efficiently silence CLDN1 expression in breast cancer cells, and silencing CLDN1 expression leads to reduced cell proliferation, migration, and invasion as well as inhibiting EMT." (PMID 26067567, 2015). "CLDN1 methylation was detected in colon cancer and has been found in breast cancer." (PMID 26198249, 2015). "We further examined the alteration of CLDN1 from six different datasets including breast invasive carcinoma (Broad, Sanger, TCGA, British Columbia, Nature, 2012 ) and breast cancer patient xenograft and found that CLDN1 was amplified among samples collected in TGCA and patient xenograft dataset." (PMID 26067567, 2015). "Putative interacting partners of claudin 1 in breast cancer." (PMID 26633531, 2015). "Moreover, elevated methylation and low expression of claudin 1 were observed in breast cancer samples from The Cancer Genome Atlas (TCGA)." (PMID 23844228, 2013). "In breast cancer, expression of claudin 1 appears to vary according to the molecular subtype." (PMID 23844228, 2013). "Studies from our laboratory and others point toward a putative tumor suppressor role of claudin 1 in breast cancer as it is frequently down regulated in human invasive breast cancer and its absence or the down regulation of its expression is associated with poor prognosis." (PMID 23721519, 2013). "Downregulation of claudin 1 via DNA promoter methylation may thus be an important determinant in breast cancer development and progression." (PMID 23844228, 2013). "Additionally, in The Cancer Genome Atlas (TCGA) breast carcinoma provisional dataset, RNAseq analysis has shown claudin 1 to be up regulated in 17/81 (21%) of basal-like tumors compared with 2/324 (<1%) of luminal A/B cases." (PMID 23721519, 2013). "However, the most prominent role for claudin 1 in breast cancer appears to be that of tumor suppressor." (PMID 23844228, 2013). "In addition, we observed that the demethylating agents, azacitidine and decitabine can upregulate claudin 1 expression in breast cancer cell lines that have a methylated claudin 1 promoter." (PMID 23844228, 2013). "Given the supposed tumor suppressor role of claudin 1 in this subtype of breast cancer, epigenetic therapy to restore claudin 1 expression might represent a viable therapeutic strategy." (PMID 23844228, 2013). "To investigate if claudin 1 downregulation has an epigenetic etiology in human breast cancer we compared gene expression and methylation data from 217 patient samples available through TCGA and from 26 breast cancer cell lines analyzed in our laboratory." (PMID 23844228, 2013). "Claudin-1 expression was inhibited in other breast cancer cell lines as well indicating that the downregulation of tight junctions represents a possible molecular mechanism that facilitates CCM in breast cancer." (PMID 24324613, 2013). "It is possible that in these breast cancer cells, claudin 1 has a different function." (PMID 23721519, 2013). "Similarly, decreased claudin-1 expression is positively correlated with the frequency of recurrence and shorter disease-free intervals in breast cancer." (PMID 24009024, 2013). "It is therefore critical to fully delineate the role of structural proteins such as claudin 1 in breast cancer as such knowledge could facilitate more effective patient management." (PMID 23721519, 2013). "Although the expression of one of these proteins, claudin 1, is down regulated in most invasive human breast cancers (HBC), we have recently shown that high levels of claudin 1, characterized tumors belonging to the very aggressive basal-like breast cancer (BLBC) subtype." (PMID 23721519, 2013). "In the present study, we demonstrated the function of claudin-1 in human breast cancer MCF-7 cells." (PMID 20937153, 2010). "We demonstrated the function of claudin-1 in human breast cancer MCF-7 cells." (PMID 20937153, 2010).
breast carcinoma (continued). "Decreased expression of claudin-1 was also correlated with breast cancer recurrence." (PMID 20937153, 2010). "In this study, we focused on the functions of claudin-1 in human breast cancer cells." (PMID 20937153, 2010). "This may suggest that CLDN1 might be involved in the development of breast cancer or other epithelial tumours." (PMID 15743508, 2005). "Even more intriguing was the observation that the A124T substitution was the only mutation detected in the CLDN1 gene in 1 of 169 brain lower grade glioma, and in 1 of 132 stomach adenocarcinoma cases, but not in over 900 breast cancers (The Cancer Genome Atlas datasets,)." (PMID 27649506, 2016). "The underlying mechanism is largely unknown, and no obvious mutations in the claudin 1 gene (CLDN1) have been identified to date in breast cancer." (PMID 27649506, 2016). "The mechanism by which CLDN1 is regulated in breast cancers is largely unknown." (PMID 27649506, 2016). "The mechanisms by which CLDN1 is regulated in breast cancer are largely unknown." (PMID 27649506, 2016). "Our finding suggests that CLDN1 may be an important therapeutic target in breast cancer." (PMID 26067567, 2015). "However, the role of CLDN1 in breast cancer is largely unexplored." (PMID 26067567, 2015). "Our results suggest that CLDN1 may be a therapeutic target in breast cancer metastasis." (PMID 26067567, 2015). "Silencing CLDN1 expression may potentially inhibit breast cancer metastasis." (PMID 26067567, 2015). "However, the role of CLDN1 in breast cancer is largely unclear." (PMID 26067567, 2015). "Therefore, overexpression of DEC1 may be adjusted through the mechanism of down-regulation of claudin-1 to promote the invasion and metastasis of breast cancer." (PMID 24758579, 2014). "Additionally, in vitro studies were carried out to examine whether claudin 1 had a direct functional role in human breast cancer." (PMID 23721519, 2013). "The mechanisms responsible for decreased claudin 1 expression are not completely understood and neither the coding sequence nor the promoter region of claudin 1 appear to be mutated in either sporadic or hereditary breast cancer patients, or in breast cancer cell lines." (PMID 23844228, 2013). "Moreover, we analyzed claudin 1 expression and methylation in 26 breast cancer cell lines." (PMID 23844228, 2013). "We also demonstrate that claudin 1 could directly contribute to breast cancer progression." (PMID 23721519, 2013). "It has been reported that BHLHE40 can promote SNAI1 and SNAI2 expression and inhibit the expression of CLDN1, CLDN4, and CDH2 in breast cancer, promoting the migration and invasion of tumor cells." (PMID 37377917, 2023). "In breast cancer and particularly in triple-negative breast cancer (TNBC), CLDN1 is a good indicator for cancer cell response to paclitaxel, doxorubicin and 5-FU." (PMID 38137355, 2023). "For example, CLDN1, CLDN3, CLDN7, CLDN16 and CLDN20 have been found to be downregulated in breast cancer, and the downregulation of these claudins appearing to be linked to a more aggressive phenotype and with poor clinical outcome." (PMID 38137355, 2023). "This study will address expression of claudin-1 exclusively in a group of TNBC patients and will be added to a long list of studies that have assessed this expression in breast cancer in general." (PMID 37102018, 2023). "In this study, breast cancer cells treated with anti-PADI4 antibodies showed decreased expression of EMT-related proteins, including vimentin, claudin-1, and N-cadherin." (PMID 37804426, 2023). "At the molecular level, CLDN1 is regulated by disintegrin and metalloproteinase-15 (ADAM15) via PI3K/Akt/mTOR signaling in breast cancer." (PMID 36620607, 2022). "Several studies showed that CLDN1 overexpression led to apoptosis in MDA-MB-361, MDA-MB-231 and Hs578T breast cancer cells." (PMID 36291810, 2022).
breast carcinoma (continued). "The subcellular co-localization of CLDN-1 and CD9 supports their interaction, and this was confirmed in many cell clines including different human breast cancer cell lines." (PMID 31952355, 2020). "LEP and CLDN1 had been both shown to induce cellular migration and epithelial to mesenchymal transition (EMT) in breast cancer cells, further suggesting a FAM83H-AS1 role in the early steps of migration." (PMID 32839509, 2020). "Immunofluorescence analysis of endogenous Claudin-1 and ADAM15 in T47D breast cancer cells also demonstrated Claudin-1 and ADAM15 co-localisation at cell-cell junctions and the cell periphery." (PMID 31467400, 2019). "In human breast cancer cell line MDA-MB-231, the expression of EPS8 and CLDN1 genes depends on SATB1, and SATB1 binding sites have been found at multiple sites near and within genes encoding CLDN1 and EPS8 (based on our unpublished ChIP-seq results)." (PMID 31830989, 2019). "To confirm this further we made use of T47D breast cancer cells that have high expression levels of endogenous ADAM15 isoforms A, C and E, as well as of Claudin-1." (PMID 31467400, 2019). "We have previously shown in vitro that the human breast cancer cell line, MCF7, that displays low endogenous claudin 1 levels was hypermethylated compared to the T47D human breast cancer cell line that expresses high claudin 1 levels." (PMID 27649506, 2016). "During the metastasis, epithelial-to-mesenchymal transition (EMT) is essential and Snail, Claudin-1 and ZEB1 are well-known markers for metastasis in breast cancer." (PMID 27625789, 2016). "Thus, the high levels of claudin 1 expression in some basal-like breast cancers has led to further speculations that claudin 1 may be a tumor-facilitator in this breast cancer subtype, as has been shown for claudin 1 in melanomas, colon cancer, and oral squamous cell carcinomas." (PMID 26633531, 2015). "We found that silencing CLDN1 expression using two different shRNAs significantly reduced cell proliferation when compared to SC transduced control cells in MDA-MB-231 and MCF7 breast cancer cells." (PMID 26067567, 2015). "To determine the role of CLDN1 in breast cancer cell migration, we performed wound healing assays on MDA-MB-231 and MCF7 cells transduced with different CLDN1 lentiviral shRNAs and SC control vectors." (PMID 26067567, 2015). "To examine the role of CLDN1 in breast cancer cells, we first silenced expression of CLDN1 in MDA-MB-231 and MCF7 cells using two lentiviral shRNA vectors which target different regions of CLDN1 gene." (PMID 26067567, 2015). "We showed that lentiviral vector mediated silencing of CLDN1 leads to inhibition of EMT in both MDA-MB-231 and MCF7 breast cancer cell lines." (PMID 26067567, 2015). "Further experiments found that the expression of claudin-1 mRNA and protein level were enhanced and reduced cell invasive ability after DEC1 gene silencing in breast cancer cell lines (MCF-7 and MDA-MB-231)." (PMID 24758579, 2014). "Specifically, breast cancer patients with absent CLDN1 had significantly poorer recurrence-free survival, and multivariate analysis showed CLDN1-negative status to be an independent risk factor for recurrence and death." (PMID 40687428, 2025). "FAM83H-AS1 deregulation is associated with migration and cell death impairment in BRCA samples and breast cancer cells, and may regulate a plethora of cancer-related gene targets, such as p63, BAX, LEP and CLDN1." (PMID 32839509, 2020). "CLDN-1 is also found to be downregulated in HER2 enriched and claudin low breast cancer subtypes." (PMID 31952355, 2020). "This study demonstrated that DOCK1 mediates growth and motility through down-regulated claudin-1 expression via the RRP1B–DNMT–claudin-1 pathway and that claudin-1 serves as an important effector in DOCK1-mediated cancer progression and metastasis in claudin-low breast cancer cells." (PMID 31717460, 2019).
breast carcinoma (continued). "We show for the first time ADAM15 isoform-, and catalytic function-dependent upregulation of Claudin-1 expression, which may be responsible for the effects of ADAM15 on cancer cell phenotypes and prognostic outcomes for breast cancer patients." (PMID 31467400, 2019). "Claudin-1 is known to induce EMT in colon, liver, nasopharyngeal carcinoma, and breast cancers." (PMID 31861759, 2019). "However, a search of The Cancer Genome Atlas (TCGA) database (a large human invasive breast cancer cohort), revealed CLDN1 was one of a group of highly methylated genes, suggesting that epigenetic factors may also play a significant role in the regulation of this gene in some breast cancer subtypes." (PMID 27649506, 2016). "To examine whether CLDN1 affected breast cancer cell survival, we performed colony formation assays in both MDA-MB-231 and MCF7 cells transduced with CLDN1 lentiviral shRNAs and SC control vectors." (PMID 26067567, 2015). "Claudin 1 has also been shown to be sufficient to exert TJ-mediated paracellular sealing in metastatic breast cancer cells in the absence of other TJ proteins." (PMID 26633531, 2015). "Although not definitively proven, claudin 1 has long been postulated to be a tumor suppressor in breast cancer, as it was observed to be frequently down regulated or absent during disease progression." (PMID 26633531, 2015). "In some studies claudin-3 and -4 are overexpressed in breast cancer and in contrast, claudin-1 and claudin-7 are down regulated, or, completely absent." (PMID 26083392, 2015). "CLDN1 expression was previously found to be relatively low in triple negative breast cancer, but was highly expressed in BRCA1-related breast cancer and high-grade basal-like breast cancer." (PMID 26067567, 2015). "Interestingly, increased levels of claudin 1 have also been reported for medullary and BRCA1-type breast cancers as well, and it was further proposed that claudin 1 expression can be used to discriminate mutation carriers from sporadic breast cancer cases." (PMID 26633531, 2015). "Despite the fact that many laboratories, including our own, suggest that claudin 1 is a tumor suppressor in invasive breast cancer, our studies also suggest that this is not the case for all breast cancers." (PMID 26633531, 2015). "The absence of CLDN1 expression is strongly suggested to be an independent adverse prognostic factor in this heterogeneous subtype of breast cancer." (PMID 25393310, 2014). "Claudin 1 overexpression has been observed in some estrogen receptor negative (ER-), basal-like breast cancers." (PMID 23844228, 2013). "Claudin 1 downregulation seems more prominent in ER+ or ER+/HER2+ luminal breast cancers, but is also a feature of some basal-like breast cancers including those belonging to the “claudin-low” subtype, which have low levels of claudin 1, 3, 4, 7 and 8 and poor prognosis." (PMID 23844228, 2013). "Claudin 1 expression is low or absent in most breast cancer samples and cell lines, in sharp contrast with the normal mammary epithelium where this protein has a typical apicolateral membrane localization." (PMID 23844228, 2013). "Recently, a report demonstrated that inhibition of MEK1 signaling did not influence expression of occludin or claudin-1 or affect tight junction function in several breast cancer cell lines." (PMID 16504032, 2006). "Previous studies reported that CLDN1 mRNA expression is absent or downregulated in the majority of breast cancer cell lines." (PMID 15743508, 2005). "Earlier ChIP assays by our group identified that the Sp1 binding site on the Cldn1 promoter in SMG-C6 cells is between −284 and −84 bp, which aligns with binding sites found in the intestinal epithelium (−133 to −61 bp) and human breast cancer epithelium (−138 to −76 bp)." (PMID 40940777, 2025).
breast carcinoma (continued). "Several studies have reported an increased expression of CLDN1 in human lung adenocarcinoma, linking it to anthracycline (including DOX) resistance and decreased penetration, and in several other tumors, including colon, hepatocellular, and pancreatic adenocarcinoma, as well as in breast cancer." (PMID 37489459, 2023). "For instance, ADAM15 catalytic activity was required for claudin-1-dependent regulation of growth and mobility of breast cancer cells, but was not required for its role in promoting pathological neovascularization in a mouse model of oxygen-induced retinopathy." (PMID 37388246, 2023). "In most of the invasive human breast cancers such as ER+ luminal A and luminal B, CLDN-1 expression is found to be downregulated, while an increased expression and cytoplasmic delocalization of CLDN-1 has been observed in some of the aggressive ER- basal-like breast cancer (BLBC) subtypes." (PMID 31952355, 2020). "Moreover, the investigation also revealed ADAM15 variant-specific and catalytic activity-dependent upregulation of the expression of the tight junction protein Claudin-1, which may help to explain some aspects of the actions of ADAM15 in breast cancer." (PMID 31467400, 2019). "In this study, we silenced expression of CLDN1 in breast cancer MDA-MB-231 and MCF7 cells using highly efficient lentiviral vector mediated CLDN1 RNA interference and found that silencing CLDN1 inhibits cell proliferation, migration, and invasion by inhibiting EMT in breast cancer cell lines." (PMID 26067567, 2015). "It is still not clear whether CLDN1 expression is correlated with different grades or stages of breast cancer." (PMID 26067567, 2015). "Additional evidence of a claudin 1 tumor suppressor role comes from in vitro studies showing that anti-claudin 1 antibodies promote transformation of MCF‐12A breast epithelial cells and re-expression of claudin 1 induces apoptosis in tridimensional cultures of MDA‐MB‐361 breast cancer cells." (PMID 23844228, 2013). "We further confirmed specificity of our findings to the colonic claudin-1 expression as similar transient overexpression of Cdx1, Cdx2 or GATA4 in human breast cancer cells (MCF-7) or renal epithelial cells (MDCK II cells) did not increase claudin-1 promoter activity." (PMID 22719836, 2012). "Further, our finding that similar overexpression of Cdx1, Cdx2 or GATA4 in the renal epithelial and breast cancer cells had no apparent effect upon claudin-1 expression suggest that this is not a universal mechanism of claudin-1 expression and is rather colon specific." (PMID 22719836, 2012). "Indeed it could be speculated that the high levels of claudin 1 observed in breast cancer may be attributed to a “bystander effect” and do not contribute or participate in tumorigenesis." (PMID 26633531, 2015). "Therefore, the expression of high claudin 1 levels in the BLBC subtype, particularly in women over 55 years of age suggests that these patients may warrant more aggressive treatment as their breast cancer may be more migratory resulting in a tendency to move away from the primary location." (PMID 23721519, 2013). "Based on the observation that claudin 1 is down regulated or absent in invasive HBC, and that an absence of claudin 1 was shown to correlate with poor prognosis and shorter patient survival time, it has been speculated that claudin 1 could be a putative tumor suppressor in breast cancer." (PMID 23721519, 2013). "Human breast cancer MCF-7 and T47 D cells were treated with or without tamoxifen, siRNA against claudin-1, or tamoxifen and claudin-1 siRNA." (PMID 20937153, 2010). "However, in yet another study though using breast cancer cells, MEK1 inhibition neither affected the mRNA or protein levels of claudin-1, occludin and/or ZO-1 nor altered the subcellular cytoplasmic distribution of claudin-1 to be more membrane specific." (PMID 20671913, 2010).